C16orf96 (chromosome 16 open reading frame 96)
Tractability: PROTAC: ubiquitination databases record sites on it.
Gene: Protein-coding gene on chromosome 16 (4,556,340 to 4,600,758, forward strand). Ensembl gene ENSG00000205832.
Subcellular location (Human Protein Atlas): Centriolar satellite
Genetic constraint (gnomAD): Loss-of-function variants: 107 observed, 101.22 expected, observed/expected ratio (o/e) 1.06, 90% interval 0.9 to 1.24. The upper end of that interval is the gene's LOEUF score, 1.24, which puts it in group 5 of 6, group 1 being the genes least tolerant of losing a copy. Missense variants: 1,584 observed, 1,482.8 expected, observed/expected ratio (o/e) 1.07, 90% interval 1.02 to 1.11. Synonymous variants: 566 observed, 602.44 expected, observed/expected ratio (o/e) 0.94, 90% interval 0.88 to 1.01.
Homologues: Orthologues: chimpanzee C16H16orf96 (94% identical), macaque C20H16orf96 (86% identical), dog C16orf96 (54% identical), mouse 4930562C15Rik (48% identical), zebrafish zpax4 (6% identical), zebrafish zp2.1 (4% identical), zebrafish zp2.3 (4% identical), zebrafish zp2.6 (4% identical), zebrafish si:zfos-1505d6.3 (4% identical), zebrafish zp2.2 (4% identical), zebrafish zp2.5 (4% identical), zebrafish zp2l1 (4% identical), and 1 more. Paralogues in human: QRICH2 (20% identical), ZP1 (6% identical), ZP2 (6% identical), ZP4 (5% identical).
Diseases named in the same sentence as C16orf96 in open-access papers:
C16orf96 is named in the same sentence as 4 diseases in open-access papers, as found by Europe PMC text mining. Sharing a sentence is not in itself a finding about the gene and the disease. The quoted sentences say what the papers report.
sarcoma (1 paper, 2019). A usually aggressive malignant neoplasm of the soft tissue or bone. "Based on these genetic association data we propose that ABCB5 and C16orf96 are novel candidate risk genes for sarcoma." (PMID 31053105, 2019). "One other gene, C16orf96, was found to have a significantly lower burden (OR = 0.58, p-value = 0.0004, q-value = 0.003) of regulatory variants in controls compared to sarcoma cases." (PMID 31053105, 2019).
cancer (1 paper, 2019). A tumor composed of atypical neoplastic, often pleomorphic cells that invade other tissues. "Following gene-based burden testing and after correction for multiple testing, two of these genes, ABCB5 and C16orf96, were determined to show statistically significant association with cancer." (PMID 31053105, 2019).
C16orf96 also shares sentences with these, for which no sentence is quoted: leukaemia (1 paper); melanoma (1).